MIR548D2 (microRNA 548d-2)
Synonyms: hsa-mir-548d-2; MIRN548D2
Gene: MicroRNA gene on chromosome 17 (67,471,489 to 67,471,585, reverse strand). Ensembl gene ENSG00000263690.
Gene Ontology:
Biological process: miRNA-mediated post-transcriptional gene silencing
Cellular component: RISC complex